LINC01667 (long independently transcribed non-coding RNA 1667)
Gene: Transcribed processed pseudogene on chromosome 21 (9,810,381 to 9,810,503, reverse strand). Ensembl gene ENSG00000280081.
Diseases named in the same sentence as LINC01667 in open-access papers:
LINC01667 is named in the same sentence as 4 diseases in open-access papers, as found by Europe PMC text mining. Sharing a sentence is not in itself a finding about the gene and the disease. The quoted sentences say what the papers report.
gastric cancer (1 paper, 2020). A primary or metastatic malignant neoplasm involving the stomach. "In order to verify whether LINC01667 has an effect on the proliferation of gastric cancer cells, we constructed LINC01667 overexpression vector." (PMID 33390953, 2020). "LINC01667 is hardly expressed in gastric tissue, but LINC01667 is highly expressed in gastric cancer cells, which suggested that LINC01667 might play an oncogenic role in gastric cancer." (PMID 33390953, 2020).
lung adenocarcinoma (1 paper, 2021). A carcinoma that arises from the lung and is characterized by the presence of malignant glandular epithelial cells. "LINC01667 can act as a sponge to regulate genes such as CCNB1, CEP55, MKI67, and TYMS, and ultimately affect the progression of lung adenocarcinoma." (PMID 34458133, 2021).
cancer (2 papers, 2021 to 2024). A tumor composed of atypical neoplastic, often pleomorphic cells that invade other tissues. "What is more, our study identified three genes (BAGE2, HAVCR1P1, and LINC01667) as potential biomarkers to discriminate healthy individuals from multiple types of cancers in general." (PMID 38414068, 2024). "The western blotting showed that knockdown inhibited the phosphorylation of P65, while overexpression of LINC01667 promoted the activation of P65, which indicated that LINC01667 could promote the development of cancer by activating the NF-κB pathway." (PMID 34458133, 2021). "Long intergenic non–protein-coding RNA 1667 (LINC01667, also known as MGC38584) plays an oncogenic role in several human cancers; however, its functional role in HCC tumorigenesis remains unknown." (PMID 34458133, 2021).
tumor (1 paper, 2021). "Knocked down LINC01667 and adding anti-tumor drugs would more significantly inhibit the proliferation rate of cells." (PMID 34458133, 2021). "In addition, we found in the GEPIA database that MEG3 is downregulated in tumor tissues, which is the opposite of the expression trend of LINC01667." (PMID 34458133, 2021).